SART3 (spliceosome associated factor 3, U4/U6 recycling protein)
Diseases named in the same sentence as SART3 in open-access papers:
SART3 is named in the same sentence as 28 diseases in open-access papers, as found by Europe PMC text mining. Sharing a sentence is not in itself a finding about the gene and the disease. The quoted sentences say what the papers report.
breast carcinoma (8 papers, 2001 to 2024). "The lncRNA LASTR is upregulated in hypoxic breast cancer and increases the fitness of breast cancer cells by regulating the activity of the U4/U6 recycling factor SART3." (PMID 36845400, 2023). "It was reported to block the RRM domain and then impaired the stability of SART3 mRNA, subsequently leading to tumor suppression in breast cancer." (PMID 34782720, 2022). "LASTR, upregulated in hypoxic breast cancer, contributes to triple-negative breast cancer cell fitness by regulating the activity of the U4/U6 recycling factor SART3." (PMID 35495133, 2022). "This study investigated expression of the SART3 antigen in breast cancer to explore an appropriate molecule for use in specific immunotherapy of breast cancer patients." (PMID 11286471, 2001). "It is known that breast cancer promote the activity of SART3 through the action of LINC02651." (PMID 38773560, 2024). "Upregulated expression of lncRNA LASTR was found in several epithelial tumors and could facilitate cancer cell fitness in hypoxic breast cancer through SART3." (PMID 36457749, 2022). "Therefore, the SART3 antigen and its peptides could be an appropriate molecule for use in specific immunotherapy of the majority of HLA-A24-positive breast cancer patients." (PMID 11286471, 2001). "The SART3 antigen was detected in all of the breast cancer cell lines tested, 30 of 40 (75%) breast cancer tissue samples, and 0 of 3 non-tumourous breast tissue samples." (PMID 11286471, 2001).
melanoma (5 papers, 2015 to 2023). A malignant, usually aggressive tumor composed of atypical, neoplastic melanocytes. "For example, SART3 expression may be a diagnostic and prognostic indicator of melanoma." (PMID 34611130, 2021).
osteosarcoma (3 papers, 2005 to 2020). A usually aggressive malignant bone-forming mesenchymal neoplasm, predominantly affecting adolescents and young adults. "Indeed, several tumor antigens such as melanoma-associated antigen (MAGE), squamous cell carcinoma antigen recognized by T cells (SART) 1, SART3 and papillomavirus binding factor are expressed in osteosarcoma and provided the rationale to develop cellular therapies for this pathology." (PMID 16188028, 2005).
squamous cell carcinoma (3 papers, 2015 to 2023). A carcinoma arising from squamous epithelial cells. "In humans, expression of SART3 is associated with squamous cell carcinoma, thus most of the studies focus on its potential role as a target of cancer immunotherapy." (PMID 37206989, 2023).
breast tumor (2 papers, 2021 to 2024). "G3BP2 (G3BP Stress Granule Assembly Factor 2) regulates breast tumor initiation by stabilizing squamous cell carcinoma antigen recognized by T cells 3 (SART3) mRNA." (PMID 39190284, 2024). "In previous work, we found that G3BP2 protein was involved in stimulation of breast tumor‐initiating cells, acting through SART3 and the pluripotency transcription factors Oct‐4 and Nanog." (PMID 33525064, 2021). "We showed previously that C108 inhibits breast tumor‐initiating cells by repression of the pluripotency transcription factors Oct‐4 and Nanog through SART3." (PMID 33525064, 2021).
colorectal cancer (2 papers, 2025). A primary or metastatic malignant neoplasm that affects the colon or rectum. "Using this approach, we have identified the T → A rs2072580 substitution in the bidirectional SART3/ISCU promoter as a potential rSNP and demonstrated its association with colorectal cancer, relying on International Cancer Genome Consortium data." (PMID 40565605, 2025).
hepatocellular carcinoma (2 papers, 2017 to 2023). A malignant tumor that arises from hepatocytes. "We investigated the role of SART3 and its associated genes in hepatocellular carcinoma (HCC) by identifying nine genes that had the strongest correlation with SART3 using the STRING website." (PMID 37632835, 2023). "To evaluate the impact of SART3 on patient survival in hepatocellular carcinoma (HCC), we conducted a comprehensive analysis of various datasets." (PMID 37632835, 2023). "The expression of SART3 in hepatoma cell lines and HCC tissues was investigated by immunofluorescence and immunohistochemical analyses." (PMID 28114424, 2017). "In this study, we examined SART3 expression in various hepatoma cell lines and HCC tissues of patients, and analyzed immune responses to SART3 using peripheral blood mononuclear cells (PBMCs) and tumor-infiltrating lymphocytes (TILs)." (PMID 28114424, 2017). "In the present study, the expression of SART3 was confirmed in 6/6 (100%) hepatoma cell lines." (PMID 28114424, 2017). "With regard to the immunogenicity of SART3, we showed that SART3-specific CTLs could be generated by stimulating PBMCs with peptides, and the CTLs were cytotoxic to hepatoma cell lines." (PMID 28114424, 2017). "SART3 was expressed in all of the hepatoma cell lines examined." (PMID 28114424, 2017). "These CTLs also exhibited cytotoxicity against hepatoma cell lines with the HLA-A24 molecule and expression of SART3, which correspond to HLE and HLF, but not against Hep3B and Huh7 cells without HLA-A24." (PMID 28114424, 2017). "The expression of SART3 was observed even in the hepatoma cell lines not expressing AFP (HLF, HLE)." (PMID 28114424, 2017).
prostate carcinoma (2 papers, 2020 to 2025). A carcinoma that arises from epithelial cells of the prostate gland. "To that extent, we found that the SART3, a RNA binding protein and a binding partner of AR, was predicted to be enriched downstream of AR-enhanced exons and underrepresented in the same region of AR-excluded exons in prostate cancer cells." (PMID 32820253, 2020).
chronic hepatitis (1 paper, 2017). An active inflammatory process affecting the liver for more than six months. "However, the expression of SART3 was also observed in non-cancerous tissues of HCC patients and liver tissue in the patients with chronic hepatitis or liver cirrhosis without HCC, although less frequently and at lower levels than in HCC tissue." (PMID 28114424, 2017).
colon cancer (1 paper, 2023).
developmental delay (1 paper, 2023). "Here, we identify recessive variants in SART3 in nine individuals presenting with intellectual disability, global developmental delay and a subset of brain anomalies, together with gonadal dysgenesis in 46,XY individuals." (PMID 37296101, 2023).
glioma (1 paper, 2022). A benign or malignant brain and spinal cord tumor that arises from glial cells (astrocytes, oligodendrocytes, ependymal cells). "Of note, nuclear Ago2 was observed in glioma cells and both SART3 and PRPF8 were pulled-down by the Ago2 immunoprecipitation." (PMID 35033060, 2022). "Using a combination of miRNA FISH and immunofluorescence (IF) techniques, we further visualized miR-10b in the nuclear SART3 speckles observed in glioma cells." (PMID 35033060, 2022). "To test this hypothesis, we transfected glioma cells with the miR-10b antisense oligonucleotide (ASO) inhibitor and examined the effects of miR-10b KD on the U6 association with SART3 and PRPF8 using iCLIP." (PMID 35033060, 2022).
Intellectual disability (1 paper, 2023). "Collectively, these findings suggest that bi-allelic SART3 variants underlie a spliceosomopathy which we tentatively propose be termed INDYGON syndrome (Intellectual disability, Neurodevelopmental defects and Developmental delay with 46,XYGONadal dysgenesis)." (PMID 37296101, 2023). "In summary, children born with recessive variants in the SART3 gene present with a hitherto-undescribed syndrome characterised by gonadal dysgenesis specific to the testis (46,XY gonadal dysgenesis), neuro-developmental defects and intellectual disability." (PMID 37296101, 2023).
liver cancer (1 paper, 2023). An epithelial or non-epithelial malignant neoplasm that arises from the liver. "We quantified SART3 expression levels in various liver cancer cell lines through qPCR analysis and observed that Huh-7 and SUN-449 had the highest SART3 expression." (PMID 37632835, 2023).
lung carcinoma (1 paper, 2022). "However, research has demonstrated that LASTR modulates the activity of the U4/U6 recycling factor SART3 to boost cancer fitness, and also modulates the activity of the miR-137/TGFA/PI3K/AKT axis to accelerate lung cancer progression." (PMID 36551318, 2022).
oral cancer (1 paper, 2018). "The SART3 antigen was detected in all of oral cancer cell lines tested." (PMID 29443735, 2018). "Therefore, the SART3 antigen might be an appropriate vaccine for oral cancer patients." (PMID 29443735, 2018).
pancreatic cancers (1 paper, 2023). "Our analysis revealed that SART3 showed a significant increase in 13 types of cancer, including liver, esophageal, and pancreatic cancers (p < 0.001)." (PMID 37632835, 2023).
schizophrenia (1 paper, 2025). A major psychotic disorder characterized by abnormalities in the perception or expression of reality. "Another investigation (392 cases, 572 controls) observed that combinations of SNPs in the RNF4 (RING finger protein 4) gene (rs1203860 and rs2282765) and in the SART3 (squamous cell carcinoma antigen recognized by T cells 3) gene (rs2287550) were associated with an increased risk of schizophrenia." (PMID 39940735, 2025). "The RNF4 and SART3 proteins have a role in the growth and development of the nervous system and alterations in them might contribute to development of schizophrenia through the defective development of cortical circuits." (PMID 39940735, 2025).
tumor (26 papers, 2003 to 2025). "The present findings suggest a close association between SART3 and tumor development as well as immune infiltration." (PMID 37632835, 2023). "SART3 is known as tumor-associated antigens detected in HCC and makes hepatocytes sensitive to immunotherapy." (PMID 37993474, 2023). "Among them, lncRNA associated with SART3 regulation of splicing(LASTR) was confirmed to be highly expressed in GC specimens compared to non-tumor specimens in this cohort." (PMID 36249015, 2022). "The SART3 gene encodes a tumor-rejection antigen, a squamous cell carcinoma antigen recognized by T-cells and is under investigation as a novel immunotherapy strategy." (PMID 33668746, 2021). "Squamous cell carcinoma antigen recognized by T cells 3 (SART3), a tumor-associated antigen expressed in many cancers, functions in tumor rejection." (PMID 28114424, 2017). "Moreover, SART3 was significantly associated with tumor immune infiltration in HCC and could upregulate the expression of immune checkpoints, making it a potential molecular target for future immunotherapy and targeted therapy in HCC." (PMID 37632835, 2023). "Genes involved in tumor neovascularization and tumor suppression such as SART3 and NEDD4, were found to be significantly differentially expressed in the loggerhead brain or gonads." (PMID 34827746, 2021). "They used a set of 11 single peptides to detect immune responses against the five tumor-associated antigens SART2, SART3, MRP3, AFP and hTERT and described an RFA-induced increase of IFN-y producing tumor-specific T cells for all of these peptides." (PMID 33006650, 2021). "On the other hand, SLC6A6 and SLC22A4 are transporters, SART3 is a tumor rejection antigen, VPS41 is involved in organelle development, SEMA4C is involved in axon guidance, and SHMT1 is an enzyme with involvement in glycine, serine, and threonine metabolism." (PMID 30973896, 2019). "The expression of SART3 in HCC tissues was examined using samples obtained from 26 HCC patients by US-guided needle tumor biopsy or surgical resection and compared with the expression in non-cancerous tissues." (PMID 28114424, 2017). "SART3 was identified as a TAA by a cDNA expression cloning method using cancer-reactive tumor-infiltrating lymphocytes." (PMID 25013909, 2014). "SART3 (squamous cell carcinoma antigen recognized by T cells 3), is an RNA-binding nuclear protein that is a tumor-rejection antigen." (PMID 19455236, 2007). "SART3 is an RNA-binding nuclear protein that is a tumor-rejection antigen." (PMID 35626021, 2022). "Another miR‐10b‐regulated splicing factor, SART3, is known as a tumor‐rejection antigen." (PMID 26881967, 2016). "For example, SART3 (Squamous cell carcinoma antigen recognized by T-cells 3), an RNA binding nuclear protein involved in pre-mRNA splicing, tumor rejection, and HIV-1 replication, has also been implicated in maintaining pluripotency of human embryonic stem cells." (PMID 26459857, 2015). "However, SART3 has also been shown to act as a tumor suppressor." (PMID 40565605, 2025). "Besides its role in pre-mRNA splicing, SART3 is a multifunctional nuclear protein involved in regulating various cellular processes, including the cell cycle, mRNA synthesis, tumor immune infiltration, stem cell proliferation and differentiation, and maintenance of pluripotency." (PMID 37632835, 2023). "In the LLC subcutaneous tumor model, the number of viable LLC target cells was also decreased by the SART3/CD40L+GM-CSF vaccine in an E/T cell ratio-dependent manner." (PMID 25013909, 2014). "Synthetic SART3 peptides bind to various mouse and human MHC haplotypes and exhibit immunogenicity as cancer vaccines in mouse tumor models and clinical studies." (PMID 25013909, 2014). "We found differences in the number and distribution of CD11c+ DCs by gene transfection of SART3, CD40L, or GM-CSF genes alone and their combination in immunohistochemistry of lymphatic organs and tumor tissues." (PMID 25013909, 2014).
tumor (continued). "Expression analysis of 11 TAAs in tumor samples confirmed that HNRPL, WHSC2, SART3, CypB, PTHrP, and UBE2V were expressed in most tumor cells, validating their immunogenicity, while pre-existing IgG responses in patient plasma further supported their potential for immune enhancement." (PMID 40333213, 2025). "Also, the availability of patient DNA from the non tumoral tissue highlighted that the SNVs identified in the tumor tissue and Chor-IN-1 cell line were mainly germline, with four exceptions involving TECTA, SART3, KEL and MUC1 genes." (PMID 28835717, 2017). "Transfection of the SART3 gene alone neither upregulated CTL activity nor induced complete tumor rejection." (PMID 25013909, 2014). "In contrast, SART3 gene transfection did not increase the number of DCs in lymphatic organs, while a small number of DCs had infiltrated into tumor tissues." (PMID 25013909, 2014). "However, administration of polyplex micelles containing the GM-CSF transgene, including GM-CSF, SART3+GM-CSF, and SART3/CD40L+GM-CSF, upregulated NK cell activity in both CT26 and LLC subcutaneous tumor models." (PMID 25013909, 2014). "In the CT26 subcutaneous tumor model, the number of viable CT26 target cells was decreased by SART3/CD40L+GM-CSF gene-loaded polyplex micelles, but not mock control, GM-CSF- or SART3+GM-CSF gene-loaded polyplex micelles." (PMID 25013909, 2014). "In contrast, other treatments (n = 5−6 in each group) with SART3 (3.9±0.6 g), GM-CSF (5.3±1.5 g), CD40L (5.7±2.7 g), CD40L+GM-CSF (4.3±3.5 g), SART3+GM-CSF (6.5±3.5 g), or SART3+CD40L (6.4±2.0 g) did not inhibit tumor growth." (PMID 25013909, 2014). "Furthermore, the expression of SART3 was detected in the HCC tissue of all patients, and was independent of the expression of AFP in the tumor." (PMID 28114424, 2017).
cancer (23 papers, 2004 to 2026). A tumor composed of atypical neoplastic, often pleomorphic cells that invade other tissues. "We discovered that LINC02657 or LASTR (lncRNA linked to SART3 control of splicing), a stress-induced lncRNA, is required for cancer growth." (PMID 38047034, 2023). "Multiple studies suggest that SART3 is closely associated with cancer." (PMID 37632835, 2023). "An increased SART3 gene expression was observable in the cells and tissues with different cancer phenotypes at the transcriptional level too." (PMID 40565605, 2025). "The SART3 gene expression is elevated in the overwhelming majority of malignant neoplasms as compared with the initial tissues, suggesting its promoting role in carcinogenesis." (PMID 40565605, 2025). "In this study, we investigated the expression of SART3 mRNA in various human cancers and corresponding normal tissues." (PMID 37632835, 2023). "LINC02657 was reported that its overexpression would keep cancer cells from programmed cell death by regulating SART3." (PMID 34790235, 2021). "LINC02657 has been named as LASTR (lncRNAassociated with SART3 regulation of splicing), which was reported to decline the fitness of cancer cells by inducing intron retention." (PMID 34196116, 2021). "Several reports conclude that SART3 is among a few targets found in many cancers with value in immunotherapy." (PMID 28584285, 2017). "In a preliminary experiment, we confirmed that incubation of human SUIT2 cancer cells with mouse SART3/CD40L/GM-CSF gene-loaded polyplex micelles resulted in expression of all transgenes in vitro." (PMID 25013909, 2014). "We have used self-antigen-derived peptides, such as SART1, SART3, and lck, in phase I clinical studies of individualised peptide vaccination for far advanced cancer patients." (PMID 15083186, 2004). "We verified the effect of SART3 knockdown in BJ cells as a non-cancer cell line." (PMID 36789492, 2023). "SART3 overexpression is also an unfavorable prognostic indicator in multiple cancers, including melanoma, altogether linking both U6 and its network of protein interactions to dysfunction in cancer and as predictors of clinical outcomes." (PMID 36754845, 2023). "Moreover, SART3 is multifunctional with involvement in gene regulation, cancer immunology, stem cell pluripotency maintenance, embryonic development, and hematopoiesis." (PMID 34611130, 2021). "In particular, the SART3 protein expression is long known to be very low in both the normal tissues and non-proliferating cells, being considerably increased in several malignant tumor cell lines and cancer tissues; this has even suggested using SART3 as a potential antigen for cancer immunotherapy." (PMID 40565605, 2025). "In addition, peptides containing SART3 epitopes are capable of generating cytotoxic T lymphocytes (CTLs) and thus have been reported to be effective in immunotherapy to treat several kinds of cancer." (PMID 28114424, 2017). "Moreover, SART3 alteration may be a favorable index for cancer diagnosis, prognosis, and therapy." (PMID 34611130, 2021). "Squamous cell carcinoma recognized by T cell-3 (SART3) is involved in RNA splicing in various cancers but not in normal tissues." (PMID 25013909, 2014).
SART3 also shares sentences with these, for which no sentence is quoted: triple-negative breast carcinoma (2 papers); Ataxia (1); embryonic carcinoma (1); leukemia (1); liver cirrhosis (1); metastatic melanoma (1); musculoskeletal disorders (1); Premature ovarian insufficiency (1).